ZBTB24 (zinc finger and BTB domain containing 24)
Description:
May be involved in BMP2-induced transcription.
Synonyms: KIAA0441; ZNF450; BIF1; PATZ2; ICF2
Tractability: PROTAC: ubiquitination databases record sites on it.
Target class: Transcription factor
Gene: Protein-coding gene on chromosome 6 (109,460,632 to 109,483,239, reverse strand). Ensembl gene ENSG00000112365.
Subcellular location: Nucleus
Subcellular location (Human Protein Atlas): Nucleoplasm; Centrosome; Cytokinetic bridge
Gene Ontology:
Molecular function: protein binding; DNA-binding transcription factor activity; RNA polymerase II cis-regulatory region sequence-specific DNA binding
Biological process: regulation of transcription by RNA polymerase II
Cellular component: nucleus
Genetic constraint (gnomAD): Loss-of-function variants: 37 observed, 63.78 expected, observed/expected ratio (o/e) 0.58, 90% interval 0.44 to 0.76. The upper end of that interval is the gene's LOEUF score, 0.76, which puts it in group 3 of 6, group 1 being the genes least tolerant of losing a copy. Missense variants: 722 observed, 886.6 expected, observed/expected ratio (o/e) 0.81, 90% interval 0.76 to 0.87. Synonymous variants: 297 observed, 325.73 expected, observed/expected ratio (o/e) 0.91, 90% interval 0.83 to 1.
Gene-disease validity (ClinGen):
ClinGen rates the evidence that ZBTB24 causes each of these diseases.
immunodeficiency-centromeric instability-facial anomalies syndrome 2 (autosomal recessive): Definitive.
Homologues: Orthologues: chimpanzee ZBTB24 (99% identical), macaque ZBTB24 (98% identical), pig ZBTB24 (92% identical), rabbit ZBTB24 (88% identical), guinea pig ZBTB24 (88% identical), rat Zbtb24 (83% identical), mouse Zbtb24 (82% identical), tropical clawed frog zbtb24 (55% identical), zebrafish zbtb24 (44% identical). Paralogues in human: ZBTB48 (19% identical), ZNF142 (18% identical), ZNF160 (18% identical), ZNF420 (18% identical), ZNF99 (18% identical), ZNF91 (18% identical), ZNF107 (18% identical), ZNF84 (18% identical), ZNF729 (17% identical), ZNF594 (17% identical), ZNF208 (17% identical), ZNF764 (17% identical), and 24 more.
Diseases named in the same sentence as ZBTB24 in open-access papers:
ZBTB24 is named in the same sentence as 25 diseases in open-access papers, as found by Europe PMC text mining. Sharing a sentence is not in itself a finding about the gene and the disease. The quoted sentences say what the papers report.
ICF syndrome (13 papers, 2018 to 2026). "Similar to all subtypes of ICF syndrome, ZBTB24 pathogenic variants lead to significant DNA hypomethylation throughout the genome." (PMID 41359419, 2026). "The main identified pathogenic defects in ICF syndrome are mutations in the DNA methyltransferase 3B (DNMT3B) gene and the zinc finger and BTB domain containing 24 (ZBTB24) gene." (PMID 34825286, 2022). "Three other genes are currently known to cause ICF syndrome upon mutation, among them DNA methyltransferase 3B (DNMT3B) (ICF1), mutations in zinc finger and BTB domain containing 24 (ZBTB24) (ICF2), and cell division cycle associated 7 gene (CDCA7) (ICF3)." (PMID 32727902, 2020). "Pathogenic variants in four genes have been shown to cause ICF syndrome: DNMT3B (ICF1), ZBTB24 (ICF2), CDCA7 (ICF3), and HELLS (ICF4)." (PMID 31066130, 2019). "Pathogenic variants in four genes have been identified to cause ICF syndrome: DNA methyltransferase 3B gene (DNMT3B; ICF1), Zinc-finger and BTB domain-containing 24 gene (ZBTB24; ICF2), cell division cycle associated 7 gene (CDCA7; ICF3) and helicase lymphoid specific gene (HELLS; ICF4)." (PMID 39167297, 2024). "A striking example was the discovery of mutations in factors of unknown function but devoid of DNMT activity, namely ZBTB24, CDCA7 and HELLS, as genetic causes of the ICF syndrome." (PMID 33916664, 2021). "Furthermore, we show that rare gnomAD ZBTB24 missense variants in key residues of the C2H2‐ZF domain lead to a loss of function phenotype that resembles ICF2, suggesting that these individuals are carriers of ICF syndrome." (PMID 31066130, 2019). "ICF syndrome patients can be classified based on the impaired gene, in addition to DNMT3B (ICF1): ZBTB24 (zinc-finger and BTB domain-containing 24, ICF2), CDCA7 (cell division cycle-associated 7, ICF3), and HELLS (helicase, lymphoid-specific, ICF4)." (PMID 31963661, 2020). "Although the relationships of ZBTB24, CDCA7, and HELLS with DNA methylation are not completely understood, the similarities between ICF syndrome types indicate a possible role for the different genes in the same molecular pathway." (PMID 31963661, 2020).
Immunodeficiency (9 papers, 2018 to 2025). Failure of the immune system to protect the body adequately from infection, due to the absence or insufficiency of some component process or substance. "The novel multi-exon deletion of ZBTB24 causes immunodeficiency, severe pneumonia and centromeric instability in the patient." (PMID 39958354, 2025). "Loss-of-function mutations of ZBTB24 cause immunodeficiency, centromeric instability, and facial anomalies syndrome 2 (ICF2)." (PMID 39277732, 2024). "For example, mutations in the Zbtb24 gene result in the methylation defects observed in the immunodeficiency, centromeric instability, and facial defect syndrome type 2 (ICF2)." (PMID 36096675, 2022). "Mutations in ZBTB24 cause immunodeficiency, centromeric instability, and facial anomalies (ICF) syndrome." (PMID 32865561, 2020). "ICF2 patients with loss of ZBTB24 suffer from immunodeficiency characterized by defective CSR." (PMID 32865561, 2020). "The functional deficit of the ZBTB24 protein closely correlates with the occurrence and development of immunodeficiency." (PMID 39958354, 2025). "Here, we functionally characterized the role of ZBTB24 in relation to the immunodeficiency by biochemical and cell biological approaches, as well as by functional analysis in patient-derived material." (PMID 32865561, 2020). "Immunodeficiency, centromeric instability, facial anomalies (ICF) syndrome is a rare autosomal recessive disorder that is caused by mutations in either DNMT3B, ZBTB24, CDCA7, HELLS, or yet unidentified gene(s)." (PMID 33082427, 2020). "Taken together, these findings show that ZBTB24 is involved in c-NHEJ during CSR, providing a molecular basis for the immunodeficiency in ZBTB24-deficient ICF2 patients." (PMID 32865561, 2020). "Immunodeficiency, centromeric instability, and facial anomalies syndrome (ICF) is a rare genetic defect that is inherited in an autosomal recessive manner, and the pathogenic genes include DNMT3B, ZBTB24, CDCA7, and HELLS." (PMID 39958354, 2025). "Our findings provide a plausible molecular explanation for the currently unexplained immunodeficiency in ICF2 and suggest a role for ZBTB24 in c-NHEJ." (PMID 32865561, 2020). "Nevertheless, the type and extent of the structural defect in the ZBTB24 protein do not completely correspond to the severity of the immunodeficiency and the complexity of the symptoms." (PMID 39958354, 2025). "Thus, we uncover ZBTB24 as a regulator of PARP1-dependent NHEJ and class-switch recombination, providing a molecular basis for the immunodeficiency in ICF2 syndrome." (PMID 32865561, 2020). "Four patients had immunodeficiency with centromeric instability and facial anomalies (ICF) due to a mutation in either DNMT3B or ZBTB24, while two patients have no identifiable mutations in ICF-causing genes despite satisfying clinical, immunologic, and cytogenetic diagnostic criteria." (PMID 30697212, 2018). "In addition, recent studies have highlighted a role for ZBTB24, CDCA7 and HELLS in Non-homologous end joining (NHEJ), a pathway involved in DNA repair but also in immunoglobulin class-switch recombination, linking LoF of ICF factors to immunodeficiency that affects most of ICF patients." (PMID 33916664, 2021).
abortion (2 papers, 2022 to 2024). the ending of pregnancy by removing a fetus or embryo before it can survive outside the uterus. "The results revealed that ZBTB24 expression was significantly lower in the decidua tissues of the RSA patient as compared to the induced abortion controls." (PMID 35038951, 2022). "Notably, reduced levels of ZBTB24 transcripts were recently observed in decidua and placental villi derived from women with recurrent spontaneous abortions (RSA)." (PMID 39040103, 2024). "To investigate the implication of ZBTB24 in RSA patients, we first compared the ZBTB24 expression profile based on the data from GEO dataset (GSE113790), which contained 3 RSA samples (RSA) and three induced abortion samples (Control)." (PMID 35038951, 2022). "In this study, ZBTB24 expression was compared between decidua tissues of RSA patients and induced abortion controls from a published dataset, which was further validated in placental villi tissues by RT-qPCR and Western blot." (PMID 35038951, 2022).
antibody deficiencies (2 papers, 2022 to 2025). "More than 18% of all patients with syndromic CIDs, including most DNMT3B/ZBTB24 mutations patients, were clinically diagnosed with antibody deficiencies before genetic evaluation." (PMID 36544766, 2022). "More than 18% of all patients with syndromic CIDs, including most cases with DNMT3B/ZBTB24 mutations, were clinically diagnosed with antibody deficiencies before genetic evaluation." (PMID 36544766, 2022). "Most patients in the ATM (92.5%) and STAT3 (AD-LOF) (89.5%) groups had similar clinical diagnoses, however, patients with DNMT3B/ZBTB24 mutations were first diagnosed with hypogammaglobulinemia (13, 68.4%), immunoglobulin A deficiency (2, 10.5%), and agammaglobulinemia (1, 5.3%)." (PMID 36544766, 2022). "It possibly stems from the shared immunologic features of hypogammaglobulinemia and normal B cell counts in the absence of remarkable facial abnormalities in our DNMT3B/ZBTB24-mutated patients." (PMID 36544766, 2022).
Primary Immunodeficiency (2 papers, 2025). "By Invitae Primary Immunodeficiency Gene Panel, we identified a novel homozygous 11 nucleotide deletion in exon 4 of the gene encoding zinc finger and BTB domain containing 24 (ZBTB24) (c.1125_1135del)." (PMID 40103177, 2025). "Low expression of ZBTB24 impedes B lymphocyte differentiation, leading to a significant decrease in immunoglobulin secretion and thus result in primary immunodeficiency." (PMID 39958354, 2025).
Allergy (1 paper, 2022). An allergy is an immune response or reaction to substances that are usually not harmful. "The patients with ATM predominantly presented ataxia/telangiectasia (46.2%) and infections (32.1%), while allergy (52.6%) and infection (94.4%) were the dominant first manifestations in STAT3 (AD-LOF) and DNMT3B/ZBTB24 mutations, respectively." (PMID 36544766, 2022).
autoimmune disorders (1 paper, 2022). "Altered phosphorylation of STAT3 in STAT3 deficiency or DNA methylation in DNMT3B and ZBTB24 are probably accounted for the autoimmunity in these diseases." (PMID 36544766, 2022). "Some organ-specific autoimmune disorders were observed in these patients including hematologic autoimmunity in patients with PNP, STIM1, ORAI1, WAS, ATM, and STAT5B mutations or early-onset inflammatory bowel disease in patients with WAS, DNMT3B, and ZBTB24 mutations." (PMID 36544766, 2022). "A comprehensive comparison in terms of demographic, clinical, and immunological features was performed between patients with and without autoimmunity and also among four mutation groups with the most registered cases including ATM, STAT3 (AD-LOF), DNMT3B/ZBTB24, and WAS mutations." (PMID 36544766, 2022).
developmental delay (1 paper, 2026). "Here we describe a patient with severe infections initiating during her first year of life, significant developmental delay and an abnormal facial shape, who carries a homozygous p.Val43Leu substitution in the BTB domain of ZBTB24." (PMID 41359419, 2026).
gastrointestinal infections (1 paper, 2024). "Although it is thought that the recurrent infections observed in ZBTB24-deficient patients with ICF2 mainly stem from the lack of memory humoral responses, our study indicates that defected B1 cell function may contribute to their commonly occurred respiratory and gastrointestinal infections." (PMID 39277732, 2024).
Intellectual disability (1 paper, 2025). "A review of known ZBTB24 variant cases revealed that different ZBTB24 variants may present similar phenotypes, such as hypogammaglobulinemia, centromeric instability, facial anomalies, motor development delay, and intellectual disability." (PMID 39958354, 2025).
pneumonia (1 paper, 2025). An acute, acute and chronic, or chronic inflammation focally or diffusely affecting the lung parenchyma, caused by an infection in one or both of the lungs (by bacteria, viruses, fungi, or mycoplasma.). "In this study, we initially identified a variant of exons 2-5 deletion of ZBTB24 associated with ICF2 in a 9-year-old girl with severe pneumonia by WES." (PMID 39958354, 2025).
prostate adenocarcinoma (1 paper, 2016). "For instance, in Prostate Adenocarcinoma, frequent copy number deletion for ZBTB24 (13%) and for ATG5 (12%) was observed." (PMID 27256984, 2016). "In contrast, in Prostate Adenocarcinoma a large number of copy number deletions were found, mainly in the ATG5 and ZBTB24 gene." (PMID 27256984, 2016).
ZBTB24 also shares sentences with these, for which no sentence is quoted: alopecia (1 paper); ataxia telangiectasia (1); autoimmune enteropathy (1); eczema (1); immune thrombocytopenic purpura (1); immunoglobulin A deficiency (1); immunoglobulin deficiency (1); infection (1); inflammatory bowel disease (1); mycobacterial infections (1); psoriasis (1); sinusitis (1); tuberculosis (1).